GYG1 (glycogenin 1)
Description:
Glycogenin participates in the glycogen biosynthetic process along with glycogen synthase and glycogen branching enzyme. It catalyzes the formation of a short alpha (1,4)-glucosyl chain covalently attached via a glucose 1-O-tyrosyl linkage to internal tyrosine residues and these chains act as primers for the elongation reaction catalyzed by glycogen synthase.
Synonyms: GYG; GSD15
Tractability: Small molecule: a structure with a bound ligand is known; it has a high-quality binding pocket. Antibody: its Gene Ontology location is reachable by antibodies, with high confidence. PROTAC: ubiquitination databases record sites on it; its protein half-life has been measured.
Gene: Protein-coding gene on chromosome 3 (148,991,408 to 149,031,775, forward strand). Ensembl gene ENSG00000163754.
Subcellular location: Cytoplasm; Nucleus
Subcellular location (Human Protein Atlas): Vesicles
Pathways (Reactome):
Disease: Glycogen storage disease type 0 (muscle GYS1); Glycogen storage disease type II (GAA); Glycogen storage disease type XV (GYG1); Myoclonic epilepsy of Lafora
Metabolism: Glycogen breakdown (glycogenolysis); Glycogen synthesis
Immune System: Neutrophil degranulation
Gene Ontology:
Molecular function: glycogenin glucosyltransferase activity; manganese ion binding; protein binding; protein homodimerization activity; glycosyltransferase activity
Biological process: glycogen biosynthetic process
Cellular component: catalytic complex; membrane; cytoplasm; cytosol; extracellular region; ficolin-1-rich granule lumen; lysosomal lumen; nucleus; secretory granule lumen
Genetic constraint (gnomAD): Loss-of-function variants: 36 observed, 34.34 expected, observed/expected ratio (o/e) 1.05, 90% interval 0.8 to 1.38. The upper end of that interval is the gene's LOEUF score, 1.38, which puts it in group 5 of 6, group 1 being the genes least tolerant of losing a copy. Missense variants: 399 observed, 395.97 expected, observed/expected ratio (o/e) 1.01, 90% interval 0.93 to 1.1. Synonymous variants: 132 observed, 150.46 expected, observed/expected ratio (o/e) 0.88, 90% interval 0.76 to 1.01.
Gene-disease validity (ClinGen):
ClinGen rates the evidence that GYG1 causes each of these diseases.
polyglucosan body myopathy type 2 (autosomal recessive): Definitive. Any polyglucosan body myopathy in which the cause of the disease is a mutation in the GYG1 gene.
Homologues: Orthologues: chimpanzee GYG1 (99% identical), macaque GYG1 (99% identical), dog GYG1 (95% identical), pig GYG1 (88% identical), guinea pig GYG1 (88% identical), rat Gyg1 (86% identical), mouse Gyg1 (82% identical), tropical clawed frog gyg1 (72% identical), zebrafish gyg1a (59% identical), zebrafish gyg1b (59% identical), Drosophila melanogaster Gyg (52% identical). Paralogues in human: GYG2 (57% identical).
Diseases named in the same sentence as GYG1 in open-access papers:
GYG1 is named in the same sentence as 42 diseases in open-access papers, as found by Europe PMC text mining. Sharing a sentence is not in itself a finding about the gene and the disease. The quoted sentences say what the papers report.
glycogen storage diseases (7 papers, 2016 to 2025). "GYG1 deficiency contributes to glycogen storage diseases and polysaccharide myopathy, hinting at its potential involvement in metabolic dysregulation associated with the disease." (PMID 38348451, 2024). "Two DCM patients with known genetic syndromes were confirmed to have pathogenic variants, a patient with glycogen storage disease XV had compound heterozygous pathogenic variants in the GYG1 gene, and another had a variant in the DMD gene in a patient with Becker muscular dystrophy." (PMID 39910139, 2025). "In addition, the first described case with a glycogenin-1 associated glycogen storage disease presented with cardiac arrest caused by arrhythmia." (PMID 27718144, 2017). "Polyglucosan body disease (PBD) is a type of glycogen storage disease (GSD) and is mainly caused by mutations in eight different human genes, namely, GYG1, GBE1, RBCK1, PFKM, EPM2A, EPM2B (NHLRC1), PRDM8, and PRKAG2." (PMID 33413275, 2021). "Understanding the differential contributions of GYG1 and GYG2 across various tissues is thus essential to unraveling the mechanisms underlying glycogen storage diseases and it could uncover new therapeutic targets." (PMID 40670355, 2025). "According to recent studies, the absence of GYG1 can cause glycogen synthesis disorders, leading to glycogen storage diseases and polysaccharide myopathy." (PMID 37139640, 2023). "Glycogenin-1 deficiency is known as a rare cause of skeletal muscle glycogen storage disease, usually without cardiomyopathy." (PMID 27718144, 2017).
Sepsis (5 papers, 2021 to 2025). Sepsis is defined as life-threatening organ dysfunction caused by a dysregulated host response to infection. "Our single-cell analysis revealed high expression of GYG1 in monocytes, neutrophils, and proliferating myeloid cells—cell populations that dominate the high-risk, innate immunity–driven sepsis subtype." (PMID 41333476, 2025). "In conclusion, our integrative multi-omics approach uncovered metabolic–immune heterogeneity in sepsis, established a robust immune–metabolic risk score system, and identified GYG1 as a potential metabolic driver of innate immune hyperactivation." (PMID 41333476, 2025). "This integrative multi-omics study established a robust immune–metabolic risk score system to predict sepsis patient outcomes and identified GYG1 as a metabolic driver of innate immune hyperactivation." (PMID 41333476, 2025). "Together, these data demonstrate that Gyg1 depletion alleviates hyperinflammation in sepsis by reducing metabolic fuel availability and dampening myeloid activation." (PMID 41333476, 2025). "This distinction highlights GYG1 as a unique upstream regulator of immunometabolic homeostasis and a potentially novel therapeutic target in sepsis." (PMID 41333476, 2025). "The observation that GYG1 knockdown via LNP–siRNA delivery ameliorated disease severity in an LPS-induced sepsis model supports its potential as a metabolic driver of immune dysregulation." (PMID 41333476, 2025). "Functional validation in an LPS-induced sepsis mouse model demonstrated that lipid nanoparticle (LNP)–mediated siRNA silencing of Gyg1 significantly ameliorated disease severity." (PMID 41333476, 2025). "The proof-of-concept intervention targeting GYG1 via LNP–siRNA delivery represents a novel strategy to modulate immune metabolism in sepsis." (PMID 41333476, 2025). "Our findings provide new insights into the metabolic–immune heterogeneity of sepsis and highlight GYG1 as a promising therapeutic target." (PMID 41333476, 2025). "Given the strong predictive performance of Gyg1 and its association with pro-inflammatory innate immune programs, we next investigated whether targeting Gyg1 could ameliorate sepsis outcomes." (PMID 41333476, 2025). "GYG1 is an enzyme of glycogen synthesis, which was up-regulated in sepsis." (PMID 38166628, 2024). "Interestingly, we identified GYG1 and RETN as diagnostic markers for sepsis in VLBW infants through WGCNA analysis and machine learning algorithms." (PMID 37139640, 2023). "Finally, ANKRD22, GPR84, GYG1, BLOC1S1, CARD11, NOG, and LRG1 were recognized as critical genes associated with sepsis molecular subtypes." (PMID 36035194, 2022). "In addition, metabolism-related genes, including PFKFB3, PRKAA1, PYGL, and GYG1, were also upregulated, which indicated their potential roles in mediating immune responses in sepsis." (PMID 34907156, 2021). "However, the role of GYG1 in sepsis in VLBW infants is unclear." (PMID 37139640, 2023). "A significant increase in the expression of GYG1 and RETN was observed in VLBW infants with sepsis in both the training and testing datasets." (PMID 37139640, 2023). "Accordingly, GYG1 and RETN were identified as candidate biomarkers for the diagnosis of sepsis in VLBW infants." (PMID 37139640, 2023). "In GSE154918 and GSE69063 datasets, ANKRD22, GPR84, GYG1, BLOC1S1, and LRG1 were all highly expressed in sepsis patients, whereas NOG and CARD11 were dramatically decreased in sepsis patients." (PMID 36035194, 2022). "Targeting GYG1 via LNP–siRNA delivery reduces glycogen availability and inflammatory output in myeloid cells, mitigating immune overactivation and improving disease outcomes in vivo, thereby highlighting its potential as a novel therapeutic target for sepsis." (PMID 41333476, 2025). "Kaplan–Meier survival analysis revealed that Gyg1 silencing markedly improved survival compared to both untreated and LNP-control siRNA-treated groups, suggesting that metabolic targeting of Gyg1 may offer therapeutic benefit in sepsis." (PMID 41333476, 2025).
Sepsis (continued). "There are remarkable differences in ANKRD22, GPR84, GYG1, BLOC1S1, CARD11, NOG, and LRG1 gene expression and enriched pathways among different molecular subgroups of sepsis, which may be the key factors leading to the heterogeneity of clinical symptoms and prognosis in patients with sepsis." (PMID 36035194, 2022).
cardiomyopathy (4 papers, 2017 to 2023). A disease of the heart muscle or myocardium proper. "Expression of mutated glycogenin-1 in the heart is deleterious, and it leads to storage of abnormal glycogen and cardiomyopathy." (PMID 31628455, 2020). "Altogether 22 patients have been diagnosed with GYG1 associated skeletal- or cardiomyopathy (for details of 19 previously reported patients see Suppl." (PMID 27718144, 2017). "Patients with glycogenin-1 deficiency and cardiomyopathy demonstrated extensive late gadolinium enhancement by cardiac MRI." (PMID 27718144, 2017). "We describe a new type of cardiomyopathy caused by a mutation in the glycogenin-1 gene (GYG1)." (PMID 27718144, 2017). "The clinical variability of GYG1 mutations therefore seems to include pure skeletal myopathy and pure cardiomyopathy that may lead to cardiac failure." (PMID 27718144, 2017). "In conclusion we have identified three unrelated patients homozygous for a missense GYG1 mutation presenting with cardiomyopathy and progressive dilatation and heart failure in two of them, demonstrating that glycogenin-1 deficiency should be considered a cause of cardiomyopathy in adults." (PMID 27718144, 2017). "Considering the relative high frequency of the GYG1 c.304G > C allele it may be anticipated that many more glycogenin-1 associated cardiomyopathy patients will be identified." (PMID 27718144, 2017). "In the future, the addition of GYG1 to cardiomyopathy gene panels will simplify the identification of these patients." (PMID 27718144, 2017). "An important question is whether expression of mutated glycogenin-1 does in fact cause cardiomyopathy since patients who completely lack glycogenin-1 because of biallelic truncating GYG1 mutations do not develop cardiomyopathy." (PMID 31628455, 2020). "However, nonfunctional glycogenin-1 but not glycogenin-2 was identified in cardiac muscle from patients with cardiomyopathy due to GYG1 missense mutations." (PMID 31628455, 2020). "The cause of cardiomyopathy and cardiac failure in glycogenin-1 deficiency is not fully understood but cellular overload of storage material leading to cell death and secondary fibrosis as demonstrated by MRI and histological investigations is a plausible explanation." (PMID 27718144, 2017). "GYG1 is also expressed in cardiac muscle, and cardiomyopathy has occasionally been reported in GSD XV, with or without skeletal muscle involvement." (PMID 32905144, 2020). "In the 2 patients with cardiomyopathy, nonfunctional glycogenin-1 was detected in the heart because it was present either with or without α-amylase digestion of the protein extract." (PMID 31628455, 2020). "In patients with cardiomyopathy due to GYG1 mutations, Western blot analysis revealed the presence of nonfunctional glycogenin-1." (PMID 31628455, 2020). "The expression of a non-functional glycogenin-1 was also described in a previous case with cardiomyopathy." (PMID 27718144, 2017).
polyglucosan body myopathy (3 papers, 2022 to 2024). "GYG1 deficiency is known to be associated with polyglucosan body myopathy and BLOC1S1 is widely recognized as a degradation substrate for IRE1alpha." (PMID 36035194, 2022). "Additionally, the GYG1 gene is associated with defects in glycogen storage (613507) and polyglucosan body myopathy (616199)." (PMID 39057025, 2024).
Lafora disease (2 papers, 2017 to 2020). Lafora disease (LD) is a rare, inherited, severe, progressive myoclonic epilepsy characterized by myoclonus and/or generalized seizures, visual hallucinations (partial occipital seizures), and progressive neurological decline. "Whether glycogenin-1 deficiency affects the balance between glycogen synthase and branching enzyme activities in muscle remains to be investigated, and there are many other factors implicated in the formation of polyglucosan such as in Lafora disease, which is another polyglucosan storage disease." (PMID 31628455, 2020). "This type of storage in muscle is not unique for glycogenin-1 deficiency but is also found in deficiency of branching enzyme, phosphofructokinase and RBCK1 and in Lafora disease among others." (PMID 27718144, 2017).
dengue (1 paper, 2022). "Of interest, we observed that several predictive genes of severe dengue, including GYG1, TOR3A, SPON2, GRAP2 and GBP2, were also highly transcribed in the ASCs and effector T cells at Day −1 in our dataset." (PMID 35345453, 2022).
endometriosis (1 paper, 2025). The growth of functional endometrial tissue in anatomic sites outside the uterine body. "This study employed an integrated multi-omics approach to identify and validate five core molecules (SRPRB, RBM3, INSIG2, GYG1, and FBXW2) demonstrating significant differential expression in both endometriosis and RIF, with robust diagnostic discriminatory power." (PMID 41462508, 2025). "Western blot analysis consistently demonstrated that the protein expression levels of SRPRB, RBM3, INSIG2, GYG1, and FBXW2 were significantly reduced in both endometriosis and RIF groups compared to the normal group, with statistical analysis validating these findings." (PMID 41462508, 2025).
glycogen storage cardiomyopathy (1 paper, 2017). "We describe three unrelated patients homozygous for a missense mutation in the GYG1 gene, presenting with glycogen storage cardiomyopathy and heart failure in two of them." (PMID 27718144, 2017).
ischemic stroke (1 paper, 2025). A stroke disorder caused by obstruction of blood flow to the brain, due to thrombotic (local blood clot formation) or embolic (due to a blood clot or other material traveling from another site) event. "Despite their known roles in cellular metabolism, the direct involvement of DBI, PGLS, GYG1, and TALDO1 in ischemic stroke remains scarce, warranting further investigation into their potential roles in stroke pathophysiology." (PMID 41342963, 2025).
malaria (1 paper, 2025). Malaria is a serious and sometimes fatal disease caused by a parasite that commonly infects a certain type of mosquito which feeds on humans. "Genes involved in ATP metabolism (EHD1), glycolysis (GYG1), and acetyl coenzyme A metabolism (NAT1) were also enriched in symptomatic and underrepresented in asymptomatic malaria." (PMID 40830592, 2025).
MELAS (1 paper, 2022). "The expression of protein involved in glycogen synthesis (Glycogenin-1) was significantly increased in MELAS patients." (PMID 36254078, 2022).
pneumococcal meningitis (1 paper, 2024). An acute purulent infection of the meninges and subarachnoid space caused by Streptococcus pneumoniae, most prevalent in children and adults over the age of 60. "Glycogenin 1 (GYG1) mRNA was significantly upregulated in the peripheral blood of children with pneumococcal meningitis." (PMID 39057983, 2024).
schizophrenia (1 paper, 2020). A major psychotic disorder characterized by abnormalities in the perception or expression of reality. "The top DMR (p = 1.87 × 10−14) spanned three probes within the gene GYG1, which was previously reported as differentially expressed in prefrontal pyramidal neurons from schizophrenia patients, leaving GYG1 as another candidate gene for schizophrenia neuropathological investigation." (PMID 32764320, 2020).
Stroke (1 paper, 2025). Sudden impairment of blood flow to a part of the brain due to occlusion or rupture of an artery to the brain. "We identified 4 proteins linked to glucose metabolism that were significantly altered post-stroke: L-lactate dehydrogenase A chain (Ldha), 6-phosphogluconolactonase (Pgls), glycogenin-1 (Gyg1), and transaldolase (Taldo1)." (PMID 41342963, 2025).
type 2 diabetic (1 paper, 2015). "In brief, GLSP in the diet of type 2 diabetic rats could reduce the blood glucose level possibly through the increasing of the gene expression level of glycogen synthesis (GS2 and GYG1) and glucose homeostasis (Insig-1 and Insig-2)." (PMID 25994182, 2015).
infection (6 papers, 2011 to 2026). The state of being infected such as from the introduction of a foreign agent such as serum, vaccine, antigenic substance or organism. "In this study, for the first time, we combined RAA-based CRISPR - Cas12a and CRISPR - Cas13a systems for simultaneous differential diagnosis of GyG1 and GyH1 infection." (PMID 40544408, 2025). "Infection also led to inclusion of exon 6 and exon 7 of gyg-1, and again this effect was largely suppressed by the G281D substitution in the dh1127 mutants." (PMID 32538777, 2020). "The expression patterns of genes related to the interaction between protein nutrition and secondary infection, such as GYG1 and AGR2 were similar to those observed by the microarray." (PMID 21698235, 2011). "Splicing of prg-2 and tos-1, which exhibited rnp-6 G281D dependent splicing remodeling upon infection, was also affected by rnp-6 RNAi, whereas gyg-1 had no detectable changes." (PMID 32538777, 2020). "From the genes selected for validation, FOXP1 tended to be higher in parasitized rats offered the LP diet compared to the other infection-diet combinations, whereas expression data for two other candidate genes (GYG1 and AGR2) were not confirmed." (PMID 21698235, 2011).
myopathy (4 papers, 2020 to 2026). A disease of the muscle in which the muscle fibers do not function properly. "Pathogenic biallelic variants in GYG1, encoding for glycogenin-1, are associated with polyglucosan bodies myopathy characterized by muscle accumulation of deposits of amylopectin-like polysaccharides (MIM 616199)." (PMID 42294501, 2026). "In the patients with GYG1 mutations and myopathy (Pt1, Pt2, and Pt3), there was accumulation of PAS-positive abnormal glycogen and polyglucosan in several muscle fibers." (PMID 31628455, 2020). "Mutations in glycogenin‐1 (GYG1) cause an adult‐onset polyglucosan body myopathy." (PMID 32905144, 2020). "In the 3 patients with myopathy (Pt1, Pt2, and Pt3) only Pt3 showed some residual presence of functional glycogenin-1 because a faint band was detected, but only after α-amylase treatment." (PMID 31628455, 2020). "We wish to highlight this rare clinical phenotype of GYG1‐related myopathy and the histological clues leading to its diagnosis." (PMID 32905144, 2020). "The complete absence of GYG1 may only cause a very late-onset asymptomatic myopathy." (PMID 32316520, 2020).
GYG1 also shares sentences with these, for which no sentence is quoted: breast carcinoma (2 papers); cancer (2); gastric cancer (2); Skeletal myopathy (2); Arrhythmia (1); Arthritis (1); atherosclerosis (1); Becker muscular dystrophy (1); cardiac arrest (1); colon carcinoma (1); connective tissue disorder (1); Co–infection (1); distal myopathy (1); glycogen storage disease XV (1); HCMV infection (1); heart failure (1); helminth infections (1); liver cancer (1); lymphopenia (1); melanoma (1); metabolic disease (1); metabolic myopathies (1); Pompe disease (1); stomach cancer (1); Thrombocytopenia (1).